RNU6-348P (RNA, U6 small nuclear 348, pseudogene)
Gene: Small nuclear RNA gene on chromosome 3 (171,504,245 to 171,504,351, reverse strand). Ensembl gene ENSG00000207114.
Homologues: Orthologues: chimpanzee U6 (97% identical), dog U6 (79% identical). Paralogues in human: RNU6-41P (92% identical), RNU6-1060P (91% identical), RNU6-116P (91% identical), RNU6-19P (91% identical), RNU6-378P (91% identical), RNU6-637P (91% identical), RNU6-1075P (90% identical), RNU6-1124P (90% identical), RNU6-12P (90% identical), RNU6-13P (90% identical), RNU6-22P (90% identical), RNU6-25P (90% identical), and 1286 more.